RBM27-POU4F3 (RBM27-POU4F3 readthrough)
Gene: Protein-coding gene on chromosome 5 (146,203,550 to 146,339,251, forward strand). Ensembl gene ENSG00000275740.
Genetic constraint (gnomAD): Loss-of-function variants: 16 observed, 101.49 expected, observed/expected ratio (o/e) 0.16, 90% interval 0.11 to 0.24. Missense variants: 875 observed, 1,095.6 expected, observed/expected ratio (o/e) 0.8, 90% interval 0.75 to 0.84. Synonymous variants: 425 observed, 382.65 expected, observed/expected ratio (o/e) 1.11, 90% interval 1.02 to 1.2.